INS (insulin)
Diseases named in the same sentence as INS in open-access papers (continued):
Sharing a sentence is not in itself a finding about the gene and the disease.
type 1 diabetes (continued). "The KoGES data did not contain information regarding serum insulin, C-peptide, and pancreatic autoantibodies that could be used to diagnose type 1 diabetes." (PMID 38276133, 2024). "Despite previous research indicating significant variations in insulin delivery accuracy between two types of insulin pump, a clinical study conducted on patients with type 1 diabetes revealed no discernible differences in HbA1c reduction between patch insulin pumps and traditional insulin pumps." (PMID 38599884, 2024). "However, a limitation was that antibodies to many individual milk proteins (bovine serum albumin, β-lactoglobuline, or bovine insulin), which have been related to type 1 diabetes in previous studies, were not available." (PMID 38906178, 2024). "Similarly, the use of prandial insulin for the management of postprandial hyperglycaemia in type 1 diabetes (T1D) relies mainly on carbohydrate-counting, without consideration of its rate of small intestinal delivery." (PMID 38589353, 2024). "There have been studies on the efficacy of two pumps in patients with type 1 diabetes; however, it is not known whether the Equil patch insulin pump has the same efficacy and safety profile as the traditional catheter insulin pump in T2DM patients." (PMID 38599884, 2024). "All the other studies (n = 6) used some form of record documentation for defining type 1 diabetes, based on physician diagnosis, listing in a national registry or International Classification of Disease (ICD) code of hospital contacts, or either lab results or insulin prescriptions." (PMID 37919779, 2023). "Most people with longstanding type 1 diabetes no longer secrete insulin." (PMID 38096190, 2023). "However, a change from basal insulin to ultra-long-acting insulin did not have a significant effect on coefficient of variation of HbA1c levels in a study with 90 individuals with type 1 diabetes." (PMID 36871019, 2023). "Type 1 diabetes, also known as juvenile diabetes or insulin-dependent diabetes, is a chronic condition characterized by the destruction of beta cells in the pancreas, resulting in the production of little or no insulin." (PMID 37872555, 2023). "When beta cells do not secrete enough insulin, type 1 diabetes develops." (PMID 36832207, 2023). "In Type 1 diabetes, insulin is not produced, a condition known as juvenile diabetes." (PMID 36774491, 2023). "Consequently, individuals diagnosed with type 1 diabetes exhibit minimal or no production of insulin and necessitate daily administration of insulin injections for their survival." (PMID 37724233, 2023). "However, they do not have evidence of autoimmunity or type 1 diabetes-related HLA and frequently do not require long-term insulin treatment." (PMID 36778553, 2023). "On the one hand, in type 1 diabetes (or insulin-dependent diabetes), the pancreas is not able to produce enough insulin to lower the level of glucose in the blood due to the destruction of insulin-producing pancreatic β cells." (PMID 37836872, 2023). "Interestingly, oxPTM-INSP-3 and oxPTM-INSP-6, but not Nt-INSP-3 or Nt-INSP-6, were able to inhibit the binding of type 1 diabetes samples to oxPTM-INS (p<0.001), but not to Nt-INS." (PMID 36207582, 2023). "Therefore, we expect that aerobic exercise in the morning can be safely performed by people with type 1 diabetes on insulin degludec without adjusting the dose and irrespective of injection time." (PMID 36879098, 2023). "Given the fact that lack of insulin can be fatal for those with type 1 diabetes, there are concerns that many, if not all, of those patients in our study who did not come for follow-up may have died without treatment." (PMID 37651138, 2023). "How insulin is essential for this process and without it, like in type 1 diabetes, you can die." (PMID 35943787, 2022).
type 1 diabetes (continued). "Type 1 diabetes (T1D) is a multifactorial disease characterized by a progressive destruction of pancreatic β cells, triggered by an autoimmune response, that leads to a lack of insulin production." (PMID 36555624, 2022). "Type 1 diabetes is a chronic condition in which the pancreas produces little or no insulin." (PMID 35808386, 2022). "Our findings support the hypothesis that matching prandial insulin dose with macronutrient content of the meal and planned physical activity is not easy, even after long duration of type 1 diabetes." (PMID 36619534, 2022). "In addition, a RCT and a pre-post interventional study with MNT based on carbohydrate counting found a positive effect on the glycemic control of adolescents with type 1 diabetes; however, the dose of insulin was not modified with the intervention." (PMID 35459205, 2022). "In type 1 diabetes, only insulin glulisine, detemir, and lispro were non-affordable in monotherapy." (PMID 32861229, 2022). "There will always be a need for insulin especially for people with type 1 diabetes, but genetic engineering of subcutaneously administered insulin might (or might not) be approaching its limits." (PMID 35275238, 2022). "Polyethylene glycol (PEG)–based conformal coating (CC) encapsulation of transplanted islets is a promising β cell replacement therapy for the treatment of type 1 diabetes without chronic immunosuppression because it minimizes capsule thickness, graft volume, and insulin secretion delay." (PMID 35767620, 2022). "Intensive insulin therapy, whether by multiple daily injections (MDI) or continuous subcutaneous insulin infusion (CSII), constitutes the fundamental therapy from the initial stages of type 1 diabetes (T1D), at all ages." (PMID 36510287, 2022). "However, the preventative success of insulin injections was not substantiated by clinical trials, despite the efficacious use of insulin in treating type I diabetes." (PMID 36297679, 2022). "Some individuals with type 1 diabetes had no insulin treatment after diagnosis, possibly accounting for cases of preserved beta cell function in autoimmune diabetes or may be related to partial remission within the short time frame after diagnosis." (PMID 35721726, 2022). "However, unlike our proposed review, findings from previously published systematic reviews were not specific to late adolescents and young adults, nor to type 1 diabetes, and/or to insulin adherence." (PMID 35673417, 2022). "Other indirect autoantigens are heat shock proteins, or their synthetic peptide counterparts such as DiaPep277, which has been used to preserve insulin control and secretion by the beta cells without producing adverse side effects in adult patients with type I diabetes." (PMID 36297679, 2022). "Therefore, this study investigated the protective effect of UA combined with insulin on renal injury in type 1 diabetic rats and its mechanism by establishing an STZ-induced type I diabetic rat model to provide a theoretical basis for the clinical application of UA on DN." (PMID 36249783, 2022). "There is no washout period in this study because insulin withdrawal in type 1 diabetes will lead to a significant increase in blood glucose and may lead to diabetic ketosis or even diabetic ketoacidosis." (PMID 36032108, 2022). "Also, as patients with residual pancreatic beta cell function required lower doses of insulin and showed a lower incidence of DKA events, regular follow-up of serum C-peptide could be considered in longitudinal management of type 1 diabetes patients." (PMID 35518934, 2022). "The number of patients on insulin analogues in the HAT study in Brazil is unavailable, but it was certainly much lower than that in our study, since the type of insulin usually provided by the health care system in Brazil for patients with type 1 diabetes is NPH and regular human insulin." (PMID 33905628, 2021).
type 1 diabetes (continued). "Type 1 diabetes is an immune-mediated disorder characterised by T cell-mediated autoimmune destruction of the β cells of the pancreas, leading to a deficit or absence of insulin." (PMID 34684518, 2021). "This somewhat unexpected finding might be explained by the fact that the control mice move on from Type 2 to Type 1 diabetes, as they showed reduced rather than enhanced insulin production." (PMID 34835247, 2021). "In addition, all patients were from a single centre, and people with type 1 diabetes on insulin pump therapy were not included." (PMID 34530819, 2021). "Two meta-analyses examined the efficacy and safety of DPP-4 inhibitors in adults with type 1 diabetes; neither found any significant improvement in hemoglobin A1c, BMI, or insulin dosage with treatment, though significant heterogeneity among studies limited the analyses." (PMID 33828529, 2021). "The absent glucagon responses to hypoglycemia in type 1 diabetes is a scenario specific to hypoglycemia, since other stimuli, including administration of amino acids, insulin withdrawal, lipopolysaccharide exposure, exercise and even meals lead to profound glucagon responses." (PMID 34405569, 2021). "So far, sotagliflozin and dapagliflozin are approved in Europe and Japan (but not the USA) as adjuncts to insulin for the management of overweight or obese people with type 1 diabetes when optimally titrated insulin alone does not provide adequate glycaemic control." (PMID 33595677, 2021). "However, carbohydrate and insulin absorption curves can not be directly measured from the glucose sensors used by type 1 diabetes patients." (PMID 34300672, 2021). "Whilst many intriguing non-insulin therapies have failed to fully meet their potential in the past few decades, hope remains that the knowledge gained has carved out paths towards better options for the prevention and management of type 1 diabetes." (PMID 33595677, 2021). "Here, we compare the effects of free insulin to insulin bound to positively charged nanofibers comprised of self-assembling amino acid compounds (AACs) with an antioxidant-modified side chain moiety (AAC2) in both in vitro and in vivo models of type 1 diabetes." (PMID 35056977, 2021). "Given the primary effect of carbohydrate on insulin secretion, it is not surprising that very low-carbohydrate diets are related to lower glycemic variability in people with type 1 diabetes and T2D, which at a basic level enables many of the positive responses observed in clinical trials." (PMID 34684300, 2021). "The Hovorka model is the simplest among the three analysed models; it describes the relationship between glucose and insulin in subjects with in Type 1 diabetes: therefore, like the UVAPadova model, it does not present a description of the secretion and the release of endogenous insulin." (PMID 34570804, 2021). "Currently, type 1 diabetes is common in adolescents and requires lifelong insulin therapy because of the elimination of pancreatic islet β-cells by the immune response, resulting in an absolute lack of insulin secretion." (PMID 33995278, 2021). "As previously reported, lipopolysaccharide infusion combined with insulin reduction resulted in profound glucagon responses in individuals with type 1 diabetes, resembling those seen in nondiabetic individuals, and demonstrating intact glucagon responsiveness to systemic inflammation." (PMID 34405569, 2021). "Notably, pancreas volume is small in people with type 1 diabetes (T1DM) when insulin secretion is absent." (PMID 33672162, 2021). "The pancreas of patients with type 1 diabetes produces almost no insulin by itself." (PMID 34367309, 2021). "Even in a streptozotocin (STZ)-induced type I diabetes model, a compensatory increase in glucose uptake was not suppressed, which strongly suggests that enhanced glucose uptake is independent of insulin and the insulin-induced translocation of GLUT4, but it does depend on energy insufficiency." (PMID 34940647, 2021).
type 1 diabetes (continued). "People with type 1 diabetes are not able to produce enough insulin." (PMID 32296622, 2020). "However, this study did not include patients with pregestational diabetes nor did it distinguish between patients with insulin-dependent and non–insulin-dependent diabetes." (PMID 33408574, 2020). "Alternative methods such as ELISAs have been developed to address some of the limitations of radioassay; however, they do not detect insulin autoantibodies, one of the earliest biomarkers for type 1 diabetes, and still consume 20–50 μL of serum per autoantibody." (PMID 33186361, 2020). "In type 1 diabetes, the pancreas does not release any insulin." (PMID 32296622, 2020). "In type 1 diabetes, the almost complete absence of insulin prevents glucose homeostasis." (PMID 33365205, 2020). "The high fold of glucose responsiveness of glucose responsive promoter may not sufficient for treatment of type I diabetes as insulin expression may require strict control and regulation." (PMID 33202992, 2020). "Conversely, only a few women (1.2%) without insulin treatment developed type 1 diabetes." (PMID 32725280, 2020). "Thus, our young subjects with type 1 diabetes seem to have preserved vascular homeostasis and absence of prothrombotic cMVs after ten years of intensive insulin treatment." (PMID 32309448, 2020). "On the contrary, acute single administration of IRAP inhibitor HFI-419 did not affect peripheral whole-body glucose handling during the glucose and insulin tolerance tests, neither in control rats nor in the streptozotocin-induced experimental rat model of diabetes mellitus type I." (PMID 33344504, 2020). "However, no data are available on the relationship between insulin dose and echocardiographic parameters of both systolic and diastolic function in type 1 diabetes." (PMID 33370380, 2020). "In Type I Diabetes, the β cells of the pancreas produce little to no insulin." (PMID 33227918, 2020). "Therefore, restoration of insulin-producing β-cells, as well as insulin-responsive cells, is a logical therapeutic strategy not only for type 1 diabetes (T1D) but also for T2D." (PMID 33198288, 2020). "It used to be argued that non-insulin-requiring adult-onset autoimmune diabetes either did not exist or was classic type 1 diabetes caught fleetingly in progression before insulin treatment was required, which would contrast with the clinical spectrum in Hashimoto’s thyroiditis." (PMID 31813006, 2020). "Nevertheless, the use of an insulin pump may prove to be burdensome for some patients, and the majority of patients with insulin-dependent diabetes still rely on multiple daily injection (MDI) therapy, in which the patient manually injects insulin doses using insulin pens or syringes." (PMID 32664432, 2020). "Type 1 Diabetes (T1D) is an autoimmune disease where the pancreas produces little to no insulin." (PMID 31790464, 2019). "Type 1 diabetes happens when the pancreas does not produce enough insulin to function properly." (PMID 30733818, 2019). "This study reported that GLUT8 translocated from an intracellular pool to the cell surface of the healthy myocardium upon insulin stimulation, and lack of insulin (aka type I Diabetes) down-regulated the total protein expression and trafficking to the myocardial plasma membrane." (PMID 31771288, 2019). "This can be ascribed to the fact that dietary patterns could, over time, mask some of the metabolic signatures associated with type 1 diabetes or it might be related to the lack of insulin in overt type 1 diabetes." (PMID 31444528, 2019). "The slow onset that distinguishes LADA from type 1 diabetes with adult onset is typically defined as absence of insulin treatment during the first 6 or 12 months following diagnosis, but this criterion has been questioned since it is subjective and depends on the judgment of the treating physician." (PMID 30971952, 2019).
type 1 diabetes (continued). "Participants meeting criteria for type 1 diabetes after age 30 who did not receive insulin at diagnosis (38%) commenced insulin a median of 12 months from diagnosis, and had similar characteristics to those commencing insulin at diagnosis." (PMID 30969375, 2019). "Therefore, with non-insulin-dependent diabetes, the insulin does not respond to the high glucose level." (PMID 31485387, 2019). "Currently, there is no universally accepted insulin treatment for type 1 diabetes." (PMID 30905141, 2019). "For individuals affected by Type 1 diabetes (T1D), a chronic disease in which the pancreas does not produce any insulin, maintaining the blood glucose (BG) concentration as much as possible within the safety range (70–180 mg/dl) allows avoiding short- and long-term complications." (PMID 30922295, 2019). "Similarly, downregulated lung Bmpr2 has also been found in a rat model of type 1 diabetes but not in the insulin-resistant OZR." (PMID 30689673, 2019). "However, this technique does not allow classification of type 1 diabetes at an individual level, and neither islet autoantibodies nor measures of endogenous insulin secretion were available in the UK Biobank population analysed." (PMID 30969375, 2019). "Since the blood glucose lowering effect of SGLT inhibition is minimal in the presence of euglycemia, and since the euglycemic action of these drugs is completely insulin independent, SGLT inhibitors might theoretically represent a valid adjunctive therapy in patients with type 1 diabetes." (PMID 30819210, 2019). "Our data suggest that SA may alleviate type 1 diabetes symptoms, or may be used in combination with insulin, and it will not be a sole treatment." (PMID 31581697, 2019). "A second randomized controlled trial (RCT) evaluating different insulin treatments during EN included 50 patients with non-type 1 diabetes who were randomly assigned to receive sliding scale subcutaneous regular insulin either with or without once daily subcutaneous glargine." (PMID 31261760, 2019). "As the variant of BACH2 could have a slightly altered Tregs function, it could not make an adjustment for the derangement of insulin‐specific autoreactive T cells in the periphery, resulting in the development of insulin‐triggered type 1 diabetes." (PMID 30970177, 2019). "SA may alleviate type 1 diabetes symptoms, or may be used in combination with insulin, but it will not be a sole treatment." (PMID 31581697, 2019). "Sixty patients with type 1 diabetes on insulin pump and 60 nondiabetic individuals were included." (PMID 29898180, 2018). "IGRP is an antigen of enormous pharmaceutical interest as it is specifically targeted during the autoimmune response taking place in both the Non-Obese Diabetic (NOD) mice and type 1 diabetes (T1D) patients leading to the destruction of insulin-producing beta cells." (PMID 30390011, 2018). "However, these patients were insulin dependent and no long-term study of any type of insulin regimen has produced long-term outcomes in type 1 diabetes like those reported here." (PMID 29880308, 2018). "Although it is important to match the rate of gastric emptying and the onset and offset of insulin action, significantly lower insulin requirements are observed in patients with type 1 diabetes with gastroparesis than those without, during the first hour of the postprandial period." (PMID 29997575, 2018). "Fructose may therefore act as an alternative to glucose in meeting energy requirements, without the need for insulin, thereby being of particular interest to patients with type 1 diabetes." (PMID 28230765, 2017). "We hypothesized that a lack of insulin reaching the liver contributes to the metabolic shift towards lipid oxidation observed in humans with type 1 diabetes and rodent models of the disease." (PMID 28192442, 2017).